NHLH1 (nescient helix-loop-helix 1)
Description:
May serve as DNA-binding protein and may be involved in the control of cell-type determination, possibly within the developing nervous system.
Synonyms: bHLHa35; HEN1; NSCL; NSCL1
Tractability: No criterion of Open Targets' tractability assessment is met for any kind of drug.
Gene: Protein-coding gene on chromosome 1 (160,367,071 to 160,372,846, forward strand). Ensembl gene ENSG00000171786.
Subcellular location: Nucleus
Subcellular location (Human Protein Atlas): Golgi apparatus
Gene Ontology:
Molecular function: DNA-binding transcription activator activity, RNA polymerase II-specific; protein binding; RNA polymerase II transcription regulatory region sequence-specific DNA binding; sequence-specific double-stranded DNA binding; DNA-binding transcription factor activity, RNA polymerase II-specific; RNA polymerase II cis-regulatory region sequence-specific DNA binding; protein dimerization activity
Biological process: positive regulation of transcription by RNA polymerase II; central nervous system development; regulation of transcription by RNA polymerase II
Cellular component: chromatin; nucleus
Genetic constraint (gnomAD): Loss-of-function variants: 3 observed, 6.49 expected, observed/expected ratio (o/e) 0.46, 90% interval 0.21 to 1.19. That is too few expected variants to judge how well the gene tolerates losing a copy. Missense variants: 177 observed, 197.27 expected, observed/expected ratio (o/e) 0.9, 90% interval 0.79 to 1.02. Synonymous variants: 92 observed, 86.76 expected, observed/expected ratio (o/e) 1.06, 90% interval 0.89 to 1.26.
Homologues: Orthologues: chimpanzee NHLH1 (100% identical), pig NHLH1 (99% identical), macaque NHLH1 (98% identical), rabbit NHLH1 (97% identical), guinea pig NHLH1 (96% identical), dog NHLH1 (95% identical), rat Nhlh1 (93% identical), mouse Nhlh1 (92% identical). Paralogues in human: NHLH2 (66% identical), TAL1 (36% identical), LYL1 (33% identical), TAL2 (24% identical).
Diseases named in the same sentence as NHLH1 in open-access papers:
NHLH1 is named in the same sentence as 13 diseases in open-access papers, as found by Europe PMC text mining. Sharing a sentence is not in itself a finding about the gene and the disease. The quoted sentences say what the papers report.
breast carcinoma (2 papers, 2011 to 2021). "The transcription factors (TFs) NHLH1 and HENMT1 showed 50% abundance with known breast cancer genes." (PMID 33593445, 2021).
Arrhythmia (1 paper, 2018). Any cardiac rhythm other than the normal sinus rhythm. "We note that, in mice, loss of the Nhlh1 gene leads to a reduced parasympathetic drive and an associated predisposition to arrhythmia." (PMID 30249045, 2018).
glioblastoma (1 paper, 2024). The most malignant astrocytic tumor (WHO grade IV). "NHLH1 has been associated with altered expression in glioblastoma patients with venous thromboembolism." (PMID 39766791, 2024).
medulloblastoma (1 paper, 2014). A malignant, invasive embryonal neoplasm arising from the cerebellum. "With this in mind, we assessed key transiently activated neural transcription factors (MATH1, NHLH1), and other temporally activated genes (NEUROD1, NHLH2, NFIB, LPPR4, DPYSL3, NEUROD2) expressed throughout granule neuron differentiation, in the medulloblastoma subgroups." (PMID 25412507, 2014).
schizophrenia (1 paper, 2024). A major psychotic disorder characterized by abnormalities in the perception or expression of reality. "Indeed, polymorphisms at NHLH1 and LBX1 loci have been associated with schizophrenia and PD symptoms, respectively." (PMID 38177910, 2024).
tumor (2 papers, 2017 to 2021). "For example, Nhlh1, which encodes a helix-loop-helix protein, was up-regulated in the Smo-OE group, and Foxd3, a tumor suppressor (Schmid and Müller, 2013), was down-regulated in the Smo-OE group." (PMID 29311816, 2017). "Meta-program C was defined by many markers of differentiated GNs including Neurod1 and Nhlh1, probably reflecting the differentiation states of tumor cells." (PMID 34210306, 2021).
NHLH1 also shares sentences with these, for which no sentence is quoted: acute myeloid leukemia (1 paper); bipolar disorder (1); bladder cancer (1); CNS tumor (1); Intellectual disability (1); stem cell leukemia (1); venous thromboembolism (1).